PFKFB3 (6-phosphofructo-2-kinase/fructose-2,6-biphosphatase 3)
Diseases named in the same sentence as PFKFB3 in open-access papers (continued):
Sharing a sentence is not in itself a finding about the gene and the disease.
tumor (continued). "The expression of PFKFB3 in OSCC is positively correlated with the amount of M2 macrophages and MVD, suggesting that PFKFB3 may promote angiogenesis OSCC indirectly by modulating TAM numbers within the primary tumor." (PMID 36105288, 2022). "Whether the presence of these heterodimers/heterotetramers is restricted to tumor cells is being investigated; however, normal melanocytes do not express PFKFB3." (PMID 36402789, 2022). "Accordingly, PFKFB3 downregulation has been shown to decrease the metastatic capacity of cancer cells by reducing vascular permeability through the tightening of VE-Cadherin-mediated endothelial junctions without affecting tumour growth." (PMID 32911833, 2020). "Lowering glycolysis by low dose pharmacological PFKFB3 inhibition using 3-(3-pyridinyl)-1-(4-pyridinyl)-2-propen-1-one (3PO) or endothelial PFKFB3 haplodeficiency did not affect tumor growth but normalized tumor vessels leading to lower cancer cell invasion, intravasation and metastasis." (PMID 30255018, 2018). "Moreover, PFKFB3 expression can be regulated by oncogenes like hypoxia-inducible factor 1-alpha (HIF-1a), RAS, mesenchymal epithelial transition (MET), phosphoinositide 3-kinases (PI3K/Akt), and phosphatase and tensin homolog (PTEN) to provide metabolic control of tumor development." (PMID 34359849, 2021). "Therefore, based on the role of PFKFB3 in angiogenesis and AAT resistance, we hypothesized that dual inhibition of PFKFB3 and VEGF could reinforce the TVN effect in GBM, thereby remodeling tumor microenvironment to create a more sustained window of opportunity to improve chemotherapy outcome." (PMID 32641990, 2020). "tRiMetF31 is a miR-34a-guided tRNA-derived fragment, and its downstream target 6-phosphofructo-2-kinase/fructose-2,6-bisphosphatase 3 (PFKFB3) reduces cancer cell invasion and metastasis by normalizing the tumor vasculature." (PMID 40265011, 2025). "Although multiple PFKFB isoforms are almost certainly co-expressed in these tumor cells, the absence of bisphosphatase activity supports the explanation that the dominantly expressed PFKFB enzyme in these cells is PFKFB3." (PMID 29263928, 2017). "Consistently, PFKFB3 inhibition in mice at circadian time (CT) 7, but not CT19 significantly reduced the growth of implanted neoplasms." (PMID 27079271, 2016).
cancer (266 papers, 2011 to 2025). A tumor composed of atypical neoplastic, often pleomorphic cells that invade other tissues. "PFKFB3 is frequently overexpressed in various cancers and is associated with lymph node metastasis and poor survival outcomes." (PMID 40735327, 2025). "PFKFB3 is overexpressed in several human cancers and is associated with poor prognosis, whereas PFKFB3 knockdown or inhibition substantially inhibits cell survival, growth, and invasiveness." (PMID 41109352, 2025). "The latest researches have shown that PFKFB3 has been associated with various aspects of cancer, including cancer cell proliferation, vascular invasiveness, drug resistance, and the TME." (PMID 37519782, 2023). "For example, MAD2L2 and LRRC61 are risk factors in most cancers, while PFKFB3, ESAM, SYNM, and LRFN5 act as protective factors in most cancers." (PMID 38124743, 2023). "PFKFB3 (6-phosphofructo-2-kinase) is the rate-limiting enzyme of glycolysis and is overexpressed in several human cancers that are associated with poor prognosis." (PMID 35804016, 2022). "PFKFB3 is associated with an increase in glycolysis within cancer cells, as seen by increases in PFKFB3 expression and phosphorylation." (PMID 35865630, 2022). "As a vital regulator of glycolysis, accumulating studies have reported that PFKFB3 is associated with many aspects of cancer, including carcinogenesis, cancer cell proliferation, vessel aggressiveness, drug resistance and tumor microenviroment." (PMID 35057732, 2022). "Our findings identify that PFKFB3 is a novel target to regulate cancer stem cells and its associated therapeutic resistance markers YAP/TAZ and ABCG2 in SCLC models." (PMID 35804016, 2022). "Conclusively, PFKFB3 constitutes a metabolic key player, which causally couples cell cycle and glucose metabolism to proliferation of cancer cells." (PMID 34234350, 2021). "In this context, PFKFB3 chromatin association correlated with both the cancer-specific synergy and the increased synergy score in resistant versus sensitive cancer cells." (PMID 34298817, 2021). "Altogether, PFKFB3 is uniquely loaded to chromatin upon cisplatin treatment during cancer transformation with increased association and faster kinetics into foci upon platinum resistance, which correlates with a potential role in FA repair." (PMID 34298817, 2021). "Mounting evidence suggests that cancerous tissues overexpress the PFKFB isoenzyme, PFKFB3, being causing enhanced proliferation of cancer cells." (PMID 34234350, 2021). "Collectively, these findings further delineate the detailed mechanism underlying lncRNA-mediated PFKFB3 turnover and cancer metabolism remodeling." (PMID 32198345, 2020). "In a previous report, PFKFB3 was overexpressed in cancer cells and associated with cancer progression." (PMID 29559632, 2018). "Another interesting issue associated with glucose metabolism and cancer cell proliferation is the influence of hypoxia on PFKFB3 and PFK1 expression." (PMID 26337471, 2015). "As this metabolic conversion has been suggested to be a hallmark of cancer, PFKFB3 has emerged as a novel target for cancer chemotherapy." (PMID 21957443, 2011). "Studies have shown that PFKFB3 linked glycolysis with cell proliferation, especially in cancer cells, yet the role of PFKFB3 in pig adipose tissue remains unknown." (PMID 39457885, 2024). "Intriguingly, the exact three glycolytic genes with the highest upregulation upon ESCRT-I deficiency (encoding HK2, ENO2 and PFKFB3) were reported to have increased expression in cancer-associated fibroblasts due to activation of JNK signaling upon compression-induced stress." (PMID 39560723, 2024). "Furthermore, we have utilized TIMER 2.0 to analyze the correlation between mutated PFKFB3 and immune infiltration in pan-cancer." (PMID 37253634, 2023). "In many types of cancer, high expression of PFKFB3 is associated with poor prognosis." (PMID 37253634, 2023). "It was observed that the PFKFB3 level was increased in colitis-associated cancer." (PMID 36016583, 2022).
cancer (continued). "PFKFB3 is linked to cancer and displays an oncogenic role in tumorigenesis." (PMID 35454815, 2022). "In addition to glycolytic rewiring, PFKFB3 is implicated in angiogenesis, continuous cell cycle progression, and cancer cell DNA repair." (PMID 34831136, 2021). "Moreover, HCT-116 cells were shown to be more susceptible to PFKFB3 inhibition by KAN0438757 than SW-1463 cancer cells, whilst HT-29 cells interestingly upregulated PFKFB3 expression upon 50 μM of KAN0438757." (PMID 33671096, 2021). "Notably, the synergies are associated with DNA-damage-induced chromatin association of PFKFB3 upon cancer transformation, which further increases upon platinum resistance." (PMID 34298817, 2021). "Interestingly, PFKFB3 has been more recently linked the onset of cancer and its activity has been explored in many cancer cells types, whereas its contribution to the angiogenic potential of tumor-associated ECs (TECs) has been less investigated." (PMID 32825713, 2020). "Simultaneously inhibiting these oncoproteins or common ligands and PFKFB3 could cause a synergistic promotion in apoptosis and cytotoxicity of cancer cells in vitro." (PMID 28977989, 2017). "Given that PFKFB3 has been reported to be regulated by critical cancer-associated signaling molecules, strategies to inhibit PFKFB3 activity may be successful in suppressing cancer cell survival." (PMID 27669567, 2016). "Moreover, the pharmacological inhibition of glycolysis has emerged as a novel strategy for treating cancer since high glycolytic activity is considered as a metabolic hallmark of cancer, PFKFB3 has been also considered as a potential target in cancer treatment." (PMID 35057732, 2022). "Consistently, we found that several downregulated genes associated with cancer cells metabolism (Pfkfb3, Fgfbp1, Gnas, Pfkfb4, Ctnnb1, and Tsta3) in the colon of EgPSC-infected mice, indicating that intraperitoneally EgPSC infection may elicit protective effect in cancer development." (PMID 36713407, 2022). "It is reported that suppression of PFKFB3 or drug inhibition of PFKFB3 increases γ‐H2AX expression but decrease RAD51 expression in some cancer cell types." (PMID 41292194, 2025). "Specifically, in KYSE-70 cells, loss of PFKFB3 can induce epithelial–mesenchymal transition (EMT) and prolong the S phase of the cell cycle, allowing cancer cells to evade the effects of 5-FU and develop resistance." (PMID 40427135, 2025). "Specifically, in KYSE-70 cells, loss of PFKFB3 can induce EMT and prolong the S phase of the cell cycle, allowing cancer cells to evade the effects of 5-FU and develop resistance." (PMID 40427135, 2025). "PFKFB3, which is upregulated in many cancers, has been proposed as a more cancer-specific therapeutic target." (PMID 41235226, 2025). "Pfkfb3 is a key regulator of glycolysis and plays a crucial role for the metabolic changes seen in rapidly proliferating cancer cells, a phenomenon known as the Warburg effect." (PMID 41573204, 2025). "As a key regulator of the glycolysis pathway, PFKFB3 has become a focus of research in a variety of cancer cells." (PMID 40427135, 2025). "Inhibition of PFKFB3 in mouse models have shown to decrease glucose uptake and increase apoptosis in cancer cells." (PMID 40022029, 2025). "Previous studies have focused on exploring the relationship between PFKFB3 and cancer cell growth, proliferation, migration and metastasis, but relatively few studies have investigated the relationship between PFKFB3 and cancer drug resistance." (PMID 40427135, 2025). "Under normal physiological conditions, the PFKFB3 gene is expressed at relatively low levels in a variety of human tissues but is overexpressed in a number of malignant tumors." (PMID 40427135, 2025). "PFKFB3 is necessary for cancer cell migration and can be activated downstream of the EGF receptor (EGFR) by extracellular signal-regulated kinase (ERK), AMP-activated kinase (AMPK) or protein kinase A (PKA) signaling." (PMID 41159217, 2025).
cancer (continued). "In small-cell lung carcinoma (SCLC), high levels of PFKFB3 in cancer stem cells (CSCs) promote resistance to DOX, ETOP, and 5-FU." (PMID 40264038, 2025). "Several cancer types have increased PFKFB3, a glycolytic enzyme for which potent inhibitors have been found." (PMID 40022029, 2025). "The role of PFKFB3 in the glycolytic pathway in cancer cells is well established, and has been under consideration for the therapeutic targeting in various cancer types." (PMID 41516095, 2025). "The small-molecule inhibitor KAN0438757, recognized as a novel PFKFB3 inhibitor, is significant in targeted therapy due to its essential role in the DNA damage response mechanism in cancer cells." (PMID 41296396, 2025). "Targeted therapy for many cancers is based on PFKFB3, which is underexpressed in normal tissues and overexpressed in malignancies of the breast, colon, ovaries, and thyroid." (PMID 40956032, 2025). "PFKFB3 gene expression is increased in cells with increased energy demands, such as rapidly proliferating cells, and several types of cancer." (PMID 40002359, 2025). "Studies indicate that overexpression of PFKFB3 drives metabolic reprogramming and supports cancer cell proliferation and survival." (PMID 41220952, 2025). "Inhibiting PFKFB3 can reduce the metabolic rate of cancer cells, offering a novel strategy for cancer treatment." (PMID 39744225, 2025). "Although the trial did not meet the desired efficacy endpoints, it underscored the therapeutic potential of targeting PFKFB3 in cancer treatment." (PMID 40735327, 2025). "PFKFB3 is a bifunctional enzyme that has greater kinase activity compared to phosphatase activity and is upregulated in cancers." (PMID 41159217, 2025). "PFKFB3 significantly impacts multiple phases of cancer progression, including proliferation, drug resistance, and angiogenesis." (PMID 40956032, 2025). "Inhibition of PFKFB3 impairs DNA repair after irradiation of cancer cells, making it a possible radiosensitization target." (PMID 40022029, 2025). "PFKFB3 is frequently upregulated in a variety of cancers, such as breast, colon, pancreatic, and prostate cancers." (PMID 40612109, 2025). "PFKFB3 inhibition can inhibit the angiogenesis of IH and induce apoptosis, which can effectively improve cancer." (PMID 41000074, 2025). "By inhibiting PFKFB3, miR-519d-3p disrupts glycolysis, reduces energy supply to cancer cells, and enhances 5-fluouracil-induced cytotoxicity." (PMID 40871106, 2025). "The recent development of novel small molecule inhibitors of PFKFB3 for therapeutic use in cancer has added a more immediate and significant relevance to these studies." (PMID 39001392, 2024). "Our data confirm a key function for PFKFB3 in regulating glycolysis in tumorigenesis in vivo and additionally provide rationale for the further development of PFKFB3 inhibitors as cancer therapeutics." (PMID 39001392, 2024). "This regulatory mechanism leads to the upregulation of PFKFB3 expression, consequently enhancing glycolytic processes and contributing to the progression of cancer." (PMID 38341583, 2024). "As a regulator of glycolysis, PFKFB3 plays a substantial role in this metabolic scenario, and a variety of cancer entities have been characterized by enhanced PFKFB3 expression, including CRC." (PMID 39007350, 2024). "This is because of their potential to specifically target cancer types that upregulate expression of PFKFB3 to increase glycolysis." (PMID 39763797, 2024). "Increased PFKFB3 activity has been reported in many cancer types, leading to the development of several inhibitors targeting this enzyme with promising results such as impaired migration and invasion capacity of cancer cells." (PMID 38790264, 2024). "PFKFB3 is overexpressed in several human cancers and promotes proliferation and migration as well as suppresses apoptosis of cancer cells." (PMID 39007350, 2024).
cancer (continued). "As accumulates of PFKFB3 in cancer metabolism, researchers have aroused increasing interest in developing inhibitors targeting PFKFB3 for anti-neoplastic therapy." (PMID 38622715, 2024). "Several reports have indicated that inhibition of PFKFB3 enhances the chemosensitivity in various cancer cells, and we then explored the role of PFKFB3 in affecting DDP resistance in DDR cells." (PMID 39295937, 2024). "PFK158, a specific inhibitor of Fructose 2,6-Bisphosphatase 3 (PFKFB3), effectively suppresses glycolysis rate to impede cancer cell proliferation and enhances the sensitivity of cancer cells towards carboplatin and cisplatin." (PMID 38577616, 2024). "In our studies, we have found that these mice have decreased PFKFB3 levels and activity and that knocking out PFKFB3 markedly impairs the growth of tumors that closely mimic human cancer." (PMID 39001392, 2024). "6-Phosphofructo-2-kinase/fructose-2,6-bisphosphatase isoform 3 (PFKFB3) is highly expressed in several cancers and plays important roles during the whole pathological process of cancer." (PMID 39295937, 2024). "In estrogen-dependent tumors, this miRNA targets PFKFB3, regulating cancer cell proliferation through GLUT1, PFKFB3, and FAK." (PMID 38793064, 2024). "Former studies have indicated that PFKFB3 exhibited nuclear-targeting property in several cancer cells and rapid proliferation cells." (PMID 39295937, 2024). "By comparing treated vs untreated cancer samples, we also found upregulation of glycolysis regulator PFKFB3 in NACT-induced monocytes." (PMID 39315092, 2024). "Protein kinase AMP-activated catalytic subunit alpha 1 (AMPK) enhances the glycolytic activity of PFKFB3 by phosphorylating PFKFB3 at Ser461, and therefore, promoting the proliferation of cancer cells." (PMID 37253634, 2023). "KEGG results showed that PFKFB3 correlated genes were involved in melanogenesis, proteoglycans in cancer, and pathways in the cancer pathway." (PMID 37253634, 2023). "Inhibiting fructose-2,6-bisphosphatase 3 (PFKFB3), which is upregulated in several cancers, repressed glycolysis and upregulated PD-L1 expression." (PMID 36768924, 2023). "Gene Set Cancer Analysis (GSCA) was utilized to investigate the potential downstream signaling pathways of PFKFB3." (PMID 36973739, 2023). "Our work demonstrated PFKFB3 is a novel substrate of Aurora-A, and a major determinant for Aurora-A-induced cancer progression." (PMID 36990998, 2023). "To analyze the roles of PFKFB3 in tumorigenesis, we screen out correlated genes of PFKFB3 in pan-cancer and the PFKFB3 interacting proteins for pathway enrichment analyses." (PMID 37253634, 2023). "We investigated the genomic alteration and genetic modification of PFKFB3 in TCGA pan-cancer using the cBioPortal." (PMID 37253634, 2023). "A dual-target drug comprising paclitaxel and the PFKFB3 inhibitor, PFK15, blocked cancer-associated fibroblast-mediated cancer cell growth and reduced the lactate concentration in the TME." (PMID 36768924, 2023). "Some studies have demonstrated the aberrant expression of PFKFB3 in cancer tissues and its role in tumorigenesis." (PMID 37253634, 2023). "PFKFB3 is an essential regulator of endothelial glycolysis metabolism, promotes angiogenesis, and thus promote metastasis in malignant tumors." (PMID 37143105, 2023). "We also observed a significant difference in the PRDX3/PFKFB3 correlation at the gene expression level, between carcinoma and hyperplasia patients, also indicative of increased systemic metabolic stress in cancer patients." (PMID 37047426, 2023). "PFK158, a structural analog of PFK-015, is also a PFKFB3 inhibitor that can exert anti-cancer effects." (PMID 36984785, 2023). "In some cancer treatment studies, the PFKFB3 gene expression level has been found to interact with proinflammatory molecules (e.g., IL-6), thus this pathological mechanism similar to OA can be extended and deserves further study." (PMID 38264652, 2023).